CXCR6 (C-X-C motif chemokine receptor 6)
Diseases named in the same sentence as CXCR6 in open-access papers (continued):
Sharing a sentence is not in itself a finding about the gene and the disease.
meningioma (1 paper, 2016). A generally slow growing tumor attached to the dura mater. "We used quantitative reverse-transcription polymerase chain reaction, immunocytochemistry and western blot to detect CXCL16 and CXCR6 in human meningioma cells isolated from 28 human meningiomas." (PMID 27784296, 2016). "We initially measured CXCL16 and CXCR6 mRNA expression in cultured meningioma cells used in our experimental settings." (PMID 27784296, 2016). "Summarized, in cultured primary human meningioma cells the classical CXCL16 receptor CXCR6 is lost, but nevertheless CXCL16 is still able to bind to and transduce signals into the cells resulting in increased proliferation and rescue of apoptosis of the cells." (PMID 27784296, 2016). "Apart from that, we could show that solid human meningiomas - the second most common intracranial tumors - are also characterized by high expression levels of CXCL16 while CXCR6 expression is more restricted." (PMID 27784296, 2016). "However, although cultured human meningioma cells lack the CXCL16-specific receptor CXCR6, stimulation with s-CXCL16 was able to transduce intracellular signaling effects." (PMID 27784296, 2016). "However, as the human cultured meningioma cells lack the corresponding receptor CXCR6, a classical receptor mediated signaling could be excluded." (PMID 27784296, 2016). "In fact, cultured human meningioma cells considerably express CXCL16, but substantially lack CXCR6, the only known CXCL16 receptor." (PMID 27784296, 2016). "We measured in a next step if cultured CXCR6-negative human primary meningioma cells were able to bind s-CXCL16 and transduce signaling effects." (PMID 27784296, 2016). "Subsequently, we stimulated cultured human tm-CXCL16-positive, CXCR6-negative meningioma cells with recombinant s-CXCL16 and analyzed binding, signaling and biological effects using RNAi silencing to verify specificity." (PMID 27784296, 2016). "Thus, we concluded that human meningioma cells cultivated from different patients samples substantially express CXCL16 expression while CXCR6 is absent." (PMID 27784296, 2016). "Additionally, CXCL16 was able to reduce caspase-3 activity after camptothecin treatment in CXCR6-negative but tm-CXCL16-positive cultured primary human meningioma cells." (PMID 27784296, 2016). "To understand which biological consequences were induced after s-CXCL16 induced “inverse signaling”, we investigated proliferation effects and whether s-CXCL16 could prevent apoptosis in CXCR6-negative but tm-CXCL16-positive cultured primary human meningioma cells." (PMID 27784296, 2016). "In the present investigation we now describe that cultured primary human meningioma cells exhibited high CXCL16 expression in vitro, whereas the CXCL16-specific chemokine receptor CXCR6 was mostly absent." (PMID 27784296, 2016). "In fact, we could show that both effects – activation of proliferation and rescue of apoptosis – were triggered by s-CXCL16 in cultured CXCR6-negative, but tm-CXCL16-positive meningioma cells." (PMID 27784296, 2016).
mesenchymal tumors (1 paper, 2025). "A dot plot revealed a progressive decrease in both expression levels and the proportion of NK cells expressing canonical cytotoxic and trafficking-associated genes (Gzma, Gzmb, Prf1, Cxcr6) from epithelial to mesenchymal tumors." (PMID 41280107, 2025).
myocardial diseases (1 paper, 2016). "The proinflammatory function of CXCL16 in myocardial diseases is supposed to be mainly mediated by interaction with the corresponding receptor CXCR6." (PMID 26499307, 2016).
myocardial ischemia (1 paper, 2021). A disorder of cardiac function caused by insufficient blood flow to the muscle tissue of the heart. "There was indeed research deeming CXCL16 can have athero-protective effect but might make plaque unstable, yet CXCR6 can prevent myocardial ischemia." (PMID 34046056, 2021).
myositis (1 paper, 2022). "CXCL16 was significantly elevated in the two disease groups, which supports the notion that CXCR6 signaling is crucial in myositis." (PMID 36330424, 2022).
ovarian adenocarcinoma (1 paper, 2019). An adenocarcinoma that arises from the ovary. "Expression of CXCR6 and CXCL16 was also quantified by flow cytometry in normal ovarian epithelial cells (IOSE-7576), highly invasive (SKOV-3) and less invasive (OVCAR-3) ovarian adenocarcinoma cell lines." (PMID 30792527, 2019).
papillary serous adenocarcinoma (1 paper, 2019). "Higher CXCR6 expression in serous papillary carcinoma tissues suggests its association with aggressive OvCa." (PMID 30792527, 2019). "Patients with serous papillary carcinoma with N-terminus CXCL16 higher than endometrioid appear to have some alternate mechanism like differential G- protein signaling after CXCR6 activation supporting their aggressive behavior." (PMID 30792527, 2019).
paraplegia (1 paper, 2023). Complete paralysis of the lower half of the body including both legs, often caused by damage to the spinal cord. "FYCO1 also has interaction potential with CCZ1B involved in vacuolar transport, ZFYVE27 (the spastic paraplegia gene), CXCR6, and SASS6 involved in centriole duplication." (PMID 37629644, 2023).
Parkinson disease (1 paper, 2026). A progressive degenerative disorder of the central nervous system characterized by loss of dopamine producing neurons in the substantia nigra and the presence of Lewy bodies in the substantia nigra and locus coeruleus. "Immune dysregulation is involved in Parkinson's disease (PD), but the roles of C-X-C motif chemokine receptor 3 (CXCR3)/chemokine receptor 6 (CXCR6) on T cells and their correlation with peripheral inflammation remain unclear." (PMID 41656499, 2026).
polyposis (1 paper, 2024). "Our analysis revealed distinct patterns: XCR1, CXCL13, and CXCR6 expression levels were diminished in M1-staged and advanced CRC cases, while CXCR6 expression was elevated in CRC patients with a history of polyposis, and CCR10 expression was heightened in lympho-invasive CRC." (PMID 39835121, 2024).
primary Sjögren’s syndrome (1 paper, 2025). "GZMK+CXCR6+CD8+ T cells are tissue-resident memory T (Trm) precursors that promote IgA+ B-cell antibody secretion in the labial glands of patients with primary Sjögren’s syndrome." (PMID 40659887, 2025).
pulmonary TB (1 paper, 2020). "This resistant phenotype is also associated with lower IFN-γ production in the lungs of CXCR6−/− mice with pulmonary TB, suggesting that IFN-γ-producing CXCR6+ T cells play pathogenic roles during Mtb infection." (PMID 33117393, 2020). "Also, we characterized the expression of CXCR6 in peripheral NK cells from active pulmonary tuberculosis (ATB) patients, individuals with latent TB infection (LTBI), and healthy volunteer donors (HD)." (PMID 33117393, 2020).
SARS-CoV infection (1 paper, 2022). "The increased numbers of proinflammatory monocytes in both the Ccr9- and Cxcr6-deficient mice suggest a potential mechanism for increased disease severity, as previous studies have implicated the levels of proinflammatory monocytes cells in lethal SARS-CoV infection." (PMID 35862771, 2022).
serous carcinoma (1 paper, 2019). "Higher expression in serous carcinoma that is aggressive histological type compared to endometrioid suggests association of CXCR6 with aggressive OvCa, which progress rapidly and poorly respond to therapeutic intervention." (PMID 30792527, 2019). "Expression of CXCR6 was significantly (p < 0.0350) higher in serous carcinoma tissues (Mean intensity/unit area = 6.6) compared to endometrioid tissues (Mean intensity/unit area = 6.323)." (PMID 30792527, 2019). "Expression of CXCR6 and N-terminal CXCL16 was significantly higher in serous carcinoma tissues compared to endometrioid." (PMID 30792527, 2019).
serous ovarian cancer (1 paper, 2021). "Analysis of the whole database of patients with high-grade serous ovarian cancer (n=280) or patients stratified for high CD8 (n=210) showed a significant correlation between CD103 and CXCR6 mRNA markers." (PMID 34607898, 2021).
Stroke (1 paper, 2022). Sudden impairment of blood flow to a part of the brain due to occlusion or rupture of an artery to the brain. "A panel of genes encoding chemokine receptors, including Ccr10, Cxcr6, and Cxcr3, was upregulated in circulating CD8+ TRLs after stroke." (PMID 35912857, 2022).
tumor (266 papers, 2009 to 2026). "For example, CXCR6-driven signaling in CTLs has been linked to the optimal positioning of these cells within specific tumor areas enriched with CXCL16-expressing dendritic cells." (PMID 39596815, 2024). "The differentially expressed GPR65, DPP4, and CXCR6 are involved in the anti-cancer efficacy of PD-1 blockade by affecting the recruitment of tumor-associated macrophages or CD8 + T cells." (PMID 38698468, 2024). "Tumor-associated macrophages promote the cisplatin resistance of OC cells by enhancing WTAP-mediated N6-methyladenosine RNA methylation via the CXCL16/CXCR6 axis." (PMID 37272931, 2023). "In two Tex clusters, we found higher expression of Cxcr6, which is associated with effector functions and tumor infiltration." (PMID 36732507, 2023). "CXCR6-deficient mice have an apparent higher tumor burden and tumor progression after intraperitoneal injection of DEN due to a reduction of iNKT and CD4 + T cells in the liver." (PMID 36773210, 2023). "In our patients, downregulation of CXCR6 associated with better tumor control and late VS recurrence." (PMID 36195959, 2022). "The authors found that CXCL16 is involved in the viability and invasion of tumor cells, while the expression of CXCR6 by cancer cells triggers oncogenic pathways associated with cancer progression and metastasis." (PMID 36311728, 2022). "Intranasal vaccination induces CXCL16 production in the lungs and is associated with infiltration by TRM expressing CXCR6, which are then required for the efficacy of anti-tumor vaccination." (PMID 36311728, 2022). "CXCR6-deficiency led to higher tumor burden in mice and lower numbers of iNKT cells and CD4+ T cells." (PMID 33578800, 2021). "CXCR6 stimulates the conversion of mesenchymal stem cells into cancer-associated fibroblasts, facilitating tumor metastasis, whereas CXCL16 promotes tumor proliferation and migration." (PMID 27618112, 2016). "CXCR6 expression in the tumor is associated with high neutrophil infiltration and poor prognosis in HCC patients." (PMID 27618112, 2016). "CXCL16 and CXCR6 are up-regulated in many cancers, and increased expression has been linked to more aggressive disease and advanced tumor stage, though few studies have shown increased expression to be independently linked to reduced survival." (PMID 26021984, 2015). "In a third part of our study, we investigated potential roles for CXCL16 and CXCR6 on tumor-associated lymphocytes." (PMID 19690611, 2009). "Additionally, CXCR6-deficient mice exhibit increased tumour metastasis in liver and lung models, highlighting the importance of this axis in limiting metastatic spread." (PMID 40361472, 2025). "Low CXCR6 expression was significantly associated with higher tumor grade." (PMID 39588301, 2024). "Indeed, our study showed that CXCR6+ KO T cells are less adherent to tumor-associated myeloid cells and are more functional when directly injected into tumor tissue." (PMID 38299146, 2023). "Recent studies have revealed that tumor-associated macrophages (TAMs) have been shown to express an M2-like phenotype promoting tumor progression and the metastasis of cancers by upregulating CXCR6 expression." (PMID 34943917, 2021). "A higher expression of CXCR6 is associated with the development of the tumor disease." (PMID 33800554, 2021). "CXCR6 + cells cause rapid increase in tumor mass compared with CXCR6- cells." (PMID 32310824, 2020). "Moreover, genes associated with TRM (CXCR6) and the Cytotoxic and Cytokine modules are all represented among tumor-associated CD8+ T cells." (PMID 31624246, 2019). "Moreover, CXCL16, a chemoattractant for CXCR6 expressing tumor cells, has been linked to an increase in tumor cell migration and invasion in prostate cancer and pancreatic ductal adenocarcinoma (PDAC)." (PMID 27618112, 2016). "However, in the present study, we could find transcript and surface expression of PD-1 in tumor infiltrating NK cells which was associated with the expression of CXCR6." (PMID 36185379, 2022).
tumor (continued). "Furthermore, CXCL16/CXCR6 interaction was required for full NK T cell and dendritic cell activation and maturation, and also mediated the adhesion of cytotoxic T cells to tumor-associated macrophages (TAM)." (PMID 28267793, 2017). "Further investigation using a CRC tumor antigen-based in vitro system for the efficient induction of CXCR6+ CD8+ T cells revealed that extracellular PUT inhibits their cytotoxic function." (PMID 41700134, 2026). "Knocking down CXCR6 in this subset considerably impaired T-cell cytotoxicity, indicating that CXCR6 engagement is necessary for effective tumor cell elimination." (PMID 41565617, 2026). "On the other hand, depletion of DE Tfh cells via Ezh2 gene deletion, inhibition of EZH2 (using FDA-approved drug, tazemetostat), or anti-CXCR6 mAb led to tumor regression." (PMID 41695367, 2026). "trNK’s enriched in tumor centers had greater enrichment of CXCR6, lower expression of CCR2, and expressed Granzyme A and Granzyme B, but not perforin." (PMID 40849493, 2025). "We provide evidence in both mice and humans that the coordinated expression of CXCR3, CCR5, and CXCR6 defines distinct CD8+ T-cell subsets with divergent roles in mediating tumor clearance and immune-related toxicity following dual checkpoint blockade." (PMID 41415437, 2025). "Tumor burden, β-catenin activation, and CXCR6 expression were assessed by tumor volume measurements, immunohistochemistry, Western blotting, and immunofluorescence." (PMID 41375019, 2025). "CXCR6 is predominantly expressed on cytotoxic T lymphocytes and plays a key role in supporting their aggregation and survival within the tumor microenvironment, thereby enhancing antitumor immunity." (PMID 41031375, 2025). "Last, but not least, there is growing evidence that CXCL9/CXCL10/CXCR3 and CXCL16/CXCR6 are involved in tumor pathogenesis, so they probably represent pleiotropic chemokines at the crossroads of immunity and carcinogenesis." (PMID 41373861, 2025). "We also annotated CXCR6+ regulatory T cells (Tregs) which potentially move toward the tumor site by CXCL16, shaping the immunosuppressive TME." (PMID 40776410, 2025). "The expanded NK cells express the chemokine receptors CXCR3, CCR5, and CXCR6, and the lung of tumor-resected mice express mRNA of the corresponding ligands CXCL9/10/11, CCL3/4/5, and CXCL16." (PMID 39835538, 2025). "DUSP4 is implicated in the development of T cell exhaustion, and we also identified overexpression of several other classically defined exhaustion marker genes such as ENTPD1, IL2RA, and CXCR6, consistent with an immune-exhausted tumor microenvironment." (PMID 40848148, 2025). "In cancer, CXCL16 exerts paradoxical roles: via CXCR6 activation, it fuels tumor proliferation, invasion, and VEGF/MMP-driven angiogenesis, yet orchestrates antitumor immunity by recruiting NKT cells." (PMID 40552145, 2025). "In terms of tumor metastasis, CXCR6 signaling stimulated the transformation of mesenchymal stem cells into cancer-associated fibroblasts, which secreted stroma-derived factor 1, also known as CXCL12." (PMID 41347146, 2025). "Incorporating immunocompetent models will also be critical to assess the therapeutic benefit of CXCR6 antagonism due to dual roles of CXCR6 in tumor-intrinsic signaling and immune recruitment." (PMID 41375019, 2025). "For example, HER2‐targeting CAR–MAIT cells infiltrate tumor tissues by expressing high levels of homing receptors, such as CXCR6 and CCR6, in breast cancer models." (PMID 41179703, 2025). "Reports have indicated that CXCR6 expression is elevated in some T cells, and these CXCR6+ T cells are recruited into tumor tissues through a CXCL16 gradient." (PMID 40452847, 2025). "Reg-1 KO CAR T cells expressed higher levels of chemokine receptors (Cxcr3, Cxcr6) that orchestrate tumor-reactive T cell infiltration and function." (PMID 40475601, 2025).